P4HTM (prolyl 4-hydroxylase, transmembrane)
Description:
Catalyzes the post-translational formation of 4-hydroxyproline in hypoxia-inducible factor (HIF) alpha proteins. Hydroxylates HIF1A at 'Pro-402' and 'Pro-564'. May function as a cellular oxygen sensor and, under normoxic conditions, may target HIF through the hydroxylation for proteasomal degradation via the von Hippel-Lindau ubiquitination complex.
Synonyms: P4H-TM; PH4; PHD4; HIFPH4; FLJ20262; EGLN4; PH-4; HIDEA
Tractability: Small molecule: an approved drug acts on it; a structure with a bound ligand is known; a high-quality ligand is known; it belongs to a druggable protein family. Antibody: UniProt predicts a signal peptide or a membrane-spanning region. PROTAC: ubiquitination databases record sites on it; its protein half-life has been measured; a small molecule that binds it is known.
Target class: Enzyme; Oxidoreductase
Gene: Protein-coding gene on chromosome 3 (48,989,889 to 49,007,153, forward strand). Ensembl gene ENSG00000178467.
Subcellular location: Endoplasmic reticulum membrane
Subcellular location (Human Protein Atlas): Cytosol; Vesicles
Gene Ontology:
Molecular function: 2-oxoglutarate-dependent dioxygenase activity; hypoxia-inducible factor-proline dioxygenase activity; protein binding; calcium ion binding; iron ion binding; L-ascorbic acid binding; oxidoreductase activity, acting on paired donors, with incorporation or reduction of molecular oxygen
Biological process: regulation of erythrocyte differentiation
Cellular component: endoplasmic reticulum membrane
Genetic constraint (gnomAD): Loss-of-function variants: 32 observed, 52.75 expected, observed/expected ratio (o/e) 0.61, 90% interval 0.46 to 0.81. The upper end of that interval is the gene's LOEUF score, 0.81, which puts it in group 3 of 6, group 1 being the genes least tolerant of losing a copy. Missense variants: 538 observed, 670.98 expected, observed/expected ratio (o/e) 0.8, 90% interval 0.75 to 0.86. Synonymous variants: 269 observed, 273 expected, observed/expected ratio (o/e) 0.99, 90% interval 0.89 to 1.09.
Homologues: Orthologues: chimpanzee P4HTM (99% identical), macaque P4HTM (96% identical), dog P4HTM (93% identical), mouse P4htm (91% identical), pig P4HTM (91% identical), rat P4htm (91% identical), rabbit P4HTM (89% identical), guinea pig P4HTM (84% identical), tropical clawed frog p4htm (63% identical), zebrafish p4htmb (50% identical), zebrafish p4htma (41% identical), Caenorhabditis elegans phy-2 (18% identical), and 29 more. Paralogues in human: P4HA1 (20% identical), P4HA3 (19% identical), P4HA2 (17% identical).
Diseases named in the same sentence as P4HTM in open-access papers:
P4HTM is named in the same sentence as 35 diseases in open-access papers, as found by Europe PMC text mining. Sharing a sentence is not in itself a finding about the gene and the disease. The quoted sentences say what the papers report.
epilepsy (4 papers, 2021 to 2025). A brain disorder characterized by episodes of abnormally increased neuronal discharge resulting in transient episodes of sensory or motor neurological dysfunction, or psychic dysfunction. "A total of seven homozygous and three compound heterozygous pathogenic P4HTM variants were identified in 18 patients with epilepsy from 11 families." (PMID 39582684, 2024). "Clinically, biallelic P4HTM variants have been identified in patients with hypotonia, hypoventilation, intellectual disabilities, dysautonomia, epilepsy, and eye abnormalities (HIDEA syndrome)." (PMID 39582684, 2024). "In patients with epilepsy associated with P4HTM variants, the only two individuals who received combination therapy were both treated with valproate and survived." (PMID 39582684, 2024). "Clinically, biallelic variants in P4HTM have been reported to cause hypotonia, hypoventilation, impaired intellectual development, dysautonomia, epilepsy, and eye abnormalities (HIDEA syndrome, OMIM# 618493)." (PMID 39582684, 2024). "Biallelic loss of function variants in P4HTM have recently been reported in association with the syndrome of hypotonia, hypoventilation, intellectual disability, dysautonomia, epilepsy and eye abnormalities (HIDEA, OMIM # 618493." (PMID 34285383, 2021). "Clinical features of patients with epilepsy associated with P4HTM variants." (PMID 39582684, 2024). "Biallelic predicted truncating P4HTM variants were identified following trio whole-genome sequencing, consistent with a diagnosis of hypotonia, hypoventilation, intellectual disability, dysautonomia, epilepsy and eye abnormalities (HIDEA) syndrome." (PMID 34285383, 2021). "However, there are limited reports describing epilepsy in patients with P4HTM variants, and the clinical features of epilepsy in this population remain unclear." (PMID 39582684, 2024). "However, the clinical features of patients with epilepsy associated with P4HTM variants remain unclear." (PMID 39582684, 2024). "The seizures observed in patients with HIDEA syndrome associated with P4HTM variants were effectively controlled, with no cases of drug-resistant epilepsy." (PMID 39582684, 2024). "Hypotonia, hypoventilation, impaired intellectual development, dysautonomia, epilepsy, and eye abnormalities (HIDEA) (OMIM #618493) is an autosomal recessive neurodevelopmental disorder caused by biallelic pathogenic variants in prolyl 4‐hydroxylase, transmembrane (P4HTM)." (PMID 35908151, 2022).
depression (3 papers, 2022 to 2025). "In addition, P4HTM null mutation results in a reduction in fear and depression." (PMID 35886042, 2022). "For major depressive disorder, we investigated P4HTM expression in both the cerebellum and cerebellar hemisphere." (PMID 38671846, 2024).
dysautonomia (3 papers, 2022 to 2024). An acute or chronic disorder, affecting the sympathetic or parasympathetic nervous system. "HIDEA syndrome was later suggested to be only caused by biallelic pathogenic mutations in P4HTM, and associates with hypotonia, hypoventilation, intellectual disability, dysautonomia, developmental delay and eye abnormalities." (PMID 37083980, 2023).
Anxiety (1 paper, 2024). Intense feelings of nervousness, tension, or panic often arise in response to interpersonal stresses. "Experimental evidence suggests that P4HTM plays a role in social behaviors and anxiety." (PMID 38671846, 2024).
breast carcinoma (1 paper, 2023). "Genomics data found that GATA3 binds to the P4HTM locus, and that ectopic expression of GATA3 in basal breast cancer cells increases the P4HTM transcript level." (PMID 36909571, 2023).
breast tumors (1 paper, 2023). "Immunohistochemical staining of breast tumors confirms co-expression between GATA3 and P4HTM at the protein level." (PMID 36909571, 2023).
Dystonia (1 paper, 2022). An abnormally increased muscular tone that causes fixed abnormal postures. "In addition, P4HTM is expressed in the basal ganglia, and P4THM deficiency may predispose to basal ganglia dysfunction leading to dystonia." (PMID 35908151, 2022).
Leigh syndrome (1 paper, 2021). A progressive neurological disease defined by specific neuropathological features associating brainstem and basal ganglia lesions. "A final possibility is that, given its location in the ER membrane, P4HTM deficiency may cause mitochondrial dysfunction by perturbation of the mitochondria-associated membranes (MAMs), as is the case in MEGDEL syndrome, a form of Leigh syndrome caused by impaired lipid remodelling in the MAMs." (PMID 34285383, 2021).
neuroblastoma (1 paper, 2024). Neuroblastoma (NB) is the most common solid, extracranial childhood tumor. "Knockdown of endogenous p4htm in neuroblastoma cells has been shown to increase HIF-1a protein levels in normoxia, and p4htm is induced by hypoxia in a cell type-specific manner." (PMID 39582684, 2024).
Obesity (1 paper, 2023). Accumulation of substantial excess body fat. "We report seven paediatric patients with severe obesity carrying rare or novel bi-allelic missense mutations in P4HTM, representing a form of monogenic syndromic obesity, following a stepwise gene-centric analysis." (PMID 37083980, 2023). "A further screening of P4HTM in other cohorts identified 2 additional subjects with severe obesity carrying homozygous missense mutations (p.Gly116Asp and p.Glu155Lys), from consanguineous families of Indian and Moroccan origin, respectively." (PMID 37083980, 2023). "Through gene-centric analysis the burden of rare, homozygous, and potentially deleterious variants in the P4HTM was significantly associated with obesity risk (Pπ = 0.013; π_hat =14; 95% CI_2.5= -26; Pτ =1.0)." (PMID 37083980, 2023). "The stepwise analysis and rigorous filtration criteria resulted in the identification of only one gene putatively involved in monogenic obesity: P4HTM (encoding Prolyl 4-Hydroxylase, Transmembrane)." (PMID 37083980, 2023). "P4HTM deficiency is a novel form of syndromic obesity affecting 1.5% of our children with obesity associated with high mortality." (PMID 37083980, 2023). "In summary, pathogenic mutations in P4HTM cause, in the SOPP cohort, severe obesity associated with neurologic features of the HIDEA syndrome in 1.5% of our probands." (PMID 37083980, 2023). "Beyond linking P4HTM to obesity, we have demonstrated the power of stepwise statistical analysis using MiST followed by stringent filtration steps in bringing to surface new genes that are also associated with obesity." (PMID 37083980, 2023).
neurodevelopmental disorder (1 paper, 2022). A behavioral and cognitive disorder with onset during the developmental period that involves impaired or aberrant development of intellectual, motor, or social functions. "HIDEA syndrome is a recognizable neurodevelopmental disorder caused by pathogenic rare or founder P4HTM variants that are likely to disrupt the P4H‐TM activity." (PMID 35908151, 2022).
neurological disorders (1 paper, 2022). "Regarding the association rs62259947: YY1 → P4HTM, P4HTM has been related to neurological disorders and social behavior." (PMID 35886042, 2022).
P4HTM also shares sentences with these, for which no sentence is quoted: Intellectual disability (3 papers); acne (1); bipolar disorder (1); chronic gastritis (1); COVID-19 (1); developmental delay (1); dorsopathies (1); early-onset epilepsy (1); Epileptic encephalopathy (1); eye abnormalities (1); hepatocellular carcinoma (1); hypotonia, hypoventilation, impaired intellectual development, dysautonomia, epilepsy, and eye abnormalities (1); immunodeficiencies (1); ischemia (1); liver fibrosis (1); MEGDEL syndrome (1); mitochondrial disease (1); myopia (1); psychiatric disorder (1); schizophrenia (1); Stroke (1); syndromic epilepsy (1); tumor (1).